CDC20 (cell division cycle 20)
Diseases named in the same sentence as CDC20 in open-access papers (continued):
Sharing a sentence is not in itself a finding about the gene and the disease.
tumor (continued). "Both in the dataset GSE25055 and GSE42568, higher expression levels of ASPM, CDC20, and TTK were related to advanced tumor grades." (PMID 31106147, 2019). "In the datasets GSE25055 and GSE42568, higher expression levels of ASPM, CDC20, and TTK correlated with advanced tumor grades." (PMID 31106147, 2019). "Upregulated BUB1B, CCNB1, CDC7, CDC20, and MCM3 in HCC tumor tissues also contributed to worse DFS in HCC patients (Log rank P = 0.000052, 0.0192, 0.0307, 0.00496, and 0.0284, respectively)." (PMID 30363964, 2018). "BUB1B, CCNB1, CDC7, CDC20, and MCM3 were all overexpressed in HCC patients with neoplasm histologic grade G3-4 compared to those with G1-2 (all P < 0.05)." (PMID 30363964, 2018). "BUB1B, CCNB1, CDC7, CDC20, and MCM3 were significantly increased in HCC patients with neoplasm histologic grade G3-4 compared to those with G1-2 (all P < 0.05)." (PMID 30363964, 2018). "Most of these interactions involved cell cycle related genes, like SPC24 and CDC20 (regulated by the anti-oncomiR miR-139), and PKMYT1 (regulated by the tumour suppressor miR-195)." (PMID 28387377, 2017). "USP44 acts as a tumor suppressor by preventing chromosome segregation errors via deubiquitylation of the anaphase promoting complex (APC) coactivator Cdc20, and USP44 deletion leads to spontaneous tumor formation, preferentially in the lungs." (PMID 27516771, 2016). "Consistent with a proposed switch in the AR driven transcriptional program with local tumour progression, we observed a consistent increase in the expression of a number of these genes in higher-grade tumours, particularly CDK1, UBE2C, CDC20 and CCNA2." (PMID 27120785, 2016). "Analysis of E2F2, CDK1, CDC20, UBE2C and the proliferation biomarker Ki67 in xenograft sections showed consistently lower levels in the shASCT2 tumours." (PMID 25693838, 2015). "Targeting CDC20 expression by RNA interference attenuated TIC proliferation, self-renewal and in vivo tumor growth." (PMID 25938542, 2015). "Our study demonstrates a novel integration of FOXM1, CDC20, and p21WAF1/CIP1 with TIC proliferation, survival and tumor growth." (PMID 25938542, 2015). "Taken together, our findings demonstrate that CDC20 downregulation attenuates TIC phenotypes including proliferation, self-renewal, and tumor formation." (PMID 25938542, 2015). "Inhibiting CDC20 stabilized p21CIP1/WAF1, resulting in repression of several genes critical to tumor growth and survival, including CDC25C, c-Myc and Survivin." (PMID 25938542, 2015). "Here, we demonstrate a novel function of CDC20 mediating TIC proliferation, self-renewal and tumor growth by connecting two key TIC nodes, FOXM1 and p21CIP1/WAF1." (PMID 25938542, 2015). "A similar analysis in BRCA1 vs BRCA2 tumours highlighted increase in PPI co-expression around the mitotic regulators CDK1, CDC20 and CKS1B and the histone deacetylases HDAC1 and HDAC6; these are known drug targets for which inhibitors have been developed." (PMID 25521701, 2014). "Among downregulated proteins, PTEN is a well known tumour suppressor in CRC, while CDC20, TNF and VCAM1 are important protooncogenes." (PMID 25594007, 2014). "We compared CDC20 protein expression levels in PDAC tissue samples with patient age; tumor size, differentiation, stage, and margin; lymph node metastasis; and disease recurrence." (PMID 22475564, 2012). "This suggested that high expression of CDC20, LPCAT1, and SPP1, as well as low expression of PON1, may affect the immune escape and cell metabolism of tumor cells, reducing TACE treatment sensitivity." (PMID 40404896, 2025). "CDC20, AURKA, and CCNF are highly expressed in a variety of tumor cell lines." (PMID 39895786, 2025). "Additionally, we assessed the correlation between CDC45, CDC20, and TPX2 with tumor stemness using Pearson correlation analysis." (PMID 39114311, 2024).
tumor (continued). "The convergence of these results emphasizes the interplay between tumor cell proliferation and immune responses, underscoring the potential for therapeutic strategies that leverage CD4+ T cells to enhance anti-tumor immunity while targeting key cell cycle regulators such as PLK1, CDK1, and CDC20." (PMID 39457373, 2024). "Based on the data presented in the correlation table, Spearman’s rho correlation analysis was conducted to assess the relationships between the expression of CDC20 and CCNB1 genes and tumor characteristics such as tumor stage (pTa, T1 andT2), grade (LG and HG), and overall survival (months)." (PMID 39795587, 2024). "To extend these finding, using TIDE (Tumor Immune Dysfunction and Exclusion), we analyzed the relationship between survival fraction and cytotoxic T lymphocyte (CTL) levels in two patient groups: CDC20-low and CDC20-high." (PMID 37528490, 2023). "Both immune-deficient and immune-competent murine models were utilized to examine the anti-tumor efficacy of CDC20 inhibition with or without the anti-PD1 antibodies, respectively." (PMID 37528490, 2023). "We and others have previously shown that CDC20 is highly expressed in GSCs compared to non-GSC tumor cells and primary human astrocytes and is required for key GSC phenotypes, including self-renewal and in vivo tumorigenicity." (PMID 35737702, 2022). "However, BUB1, CCNB1, BUB1B, KIF11, CDC20, TTK, and NCAPG, which are closely related to regulation of the cell cycle and DNA repair, showed strong positive correlations with tumor purity in luminal-type BC." (PMID 34733851, 2021). "CDC20, as a hub gene in HCC, plays a crucial role in tumor proliferation by governing PHD3 protein." (PMID 34900444, 2021). "The tumor xenografts in immune-competent mice with or without CDC20 knockdown were shown to have a dramatic shrinkage in tumor volume, compared with the knockdown of CDC20 in the immune-deficient mice model as previous reproted." (PMID 34527589, 2021). "Finally, genes involved in cell cycle regulation and tumor growth like CDK16, CDC20 and the Ras homologue enriched in brain (RHEB) were ubiquitously expressed in our established CSCs." (PMID 33800955, 2021). "Based on downstream analysis, 5 hub genes, including CDK1, CDC20, CCNB1, CENPF, and MAD2L1, that could play a critical role in the early diagnosis, tumour stage, and poor outcomes of HBV-HCC were identified." (PMID 34603487, 2021). "We analyzed the anti-tumor effects of AQP3, CDC20 and COL4A2 targeting alone and in combinations." (PMID 34681181, 2021). "To examine whether the radioresistant effect of CDC20 in vivo was the result of apoptosis, we performed Terminal dexynucleotidyl Transferase (TdT)-mediated dUTP nick end labeling (TUNEL) assays in tumor tissues." (PMID 32932732, 2020). "To investigate the relationship between CDC20 and tumour immunity, we analysed the relationship between CDC20 and immune cell infiltration via the TIMER website, and we found that CDC20 is involved in the infiltration of B cells, CD8+ T cells, and dendritic cells in BLCA." (PMID 32047816, 2020). "Herein, we reported that miR-138-5p could decrease the expression levels of CDC20, CCND3, Ki67, and MCM in tumor cells." (PMID 32754587, 2020). "In addition, PDAC patients with neoplasms of histologic grade G3-4 had significantly higher BUB1B, CCNA2, and CDC20 levels than those with grade G1-2 neoplasms (all P<0.05), and high levels of BUB1B and CDC20 contributed to tumor formation (both P<0.05)." (PMID 30765611, 2019). "In addition, PDAC patients with neoplasms of histologic grade G3-4 had significantly higher BUB1B, CCNA2 and CDC20 levels (all P<0.05)." (PMID 30765611, 2019).
tumor (continued). "Bub1bN and Bub1bΔN, however, were unable to ameliorate the tumor burden of KrasLA1 mice, indicating that binding of Cdc20 mediated by the N-terminal domain is necessary, but not sufficient, to protect against tumor formation." (PMID 27528194, 2016). "Based on the role of CDCD20 in regulating mitosis and cell growth our findings suggest that CDC20 expression may has a role in maintaining human PDAC cell mitosis and thus facilitating tumor growth." (PMID 22475564, 2012). "Activation of APC by Cdc20 triggers chromosome segregation by ubiquitination of securin and cyclin B. Dysfunction of the SAC leads to aneuploidy and its reliable function is important for tumor suppression." (PMID 23071525, 2012). "Furthermore, to investigate the relationship between PBRM1 and CDC20 in RCC patients, we collected 91 tumor tissues from patients in our hospital, and immunohistochemistry was performed to detect the expression of PBRM1 and CDC20 by using IHC score calculations." (PMID 39656940, 2025). "However, the potential molecular mechanism of CDC20 may be related to Scaffold Matrix Attachment Region-Binding Protein 1 (SMAR1), a tumor suppressor." (PMID 39114311, 2024). "However, CDC20 expression and tumor grade (LG vs. HG) did not appear to significantly influence overall survival, as shown by the non-significant log-rank p-values (p = 0.450 and p = 0.891, respectively) and comparable median survival times in these groups." (PMID 39795587, 2024). "For instance, CDC20, a known regulator of the cell cycle, may facilitate rapid tumor cell division, while CCNB1’s involvement in the G2/M transition could enhance the proliferative capacity of tumor cells." (PMID 39596419, 2024). "The absence of a significant correlation between CDC20 expression and tumor stage suggests that its impact may be more closely tied to histological differentiation rather than the extent of tumor invasion or spread." (PMID 39795587, 2024). "Therefore, TET2 and EZH2 play a tumor-inhibiting role in AML that affects CIN via MAD2 and CDC20." (PMID 32066746, 2020). "We examined changes in aerobic glycolysis in CDC20-silenced cells and control cells using Seahorse XF analyzers to evaluate whether CIN cells altered their metabolism in the presence of acidic medium to resemble early tumor-like cells." (PMID 32322666, 2020). "Moreover, overexpression of CDK1, CCNB1, CDC20, BUB1, MAD2L1, and BUB1B in tumour tissues could increase cell proliferation and division." (PMID 33035258, 2020). "However, tumor-free survival did not significantly differ among the kRas/Akt3, kRas/Akt3/Cdc20, and kRas/Akt3/c-Myc mice." (PMID 26993778, 2016). "Additionally, analysis of BUB1 mRNA expression in the TCGA MPM dataset—as an indicator of tumor cell proliferation—revealed a strong positive correlation between BUB1 expression and well-established proliferation and cell cycle markers, Ki67, PCNA, CCNB1, and CDC20." (PMID 40180891, 2025). "In addition, we found that the expression of RUNX1, CDC20 and MCM2 correlated with the infiltration of tumor immune cells through bioinformatics analysis, and their expression may cause the tumor immune cells to be exhausted, and the possible mechanism of action remains to be investigated." (PMID 38886545, 2024). "Furthermore, as the tumor status changed with treatment, the expression levels of these genes changed correspondingly in PBMCs; treated HCC patients without active/residual tumor cells had higher transcript levels of CCNB1, CDC20, and CENPF compared with the other two subgroups of HCC patients." (PMID 34660300, 2021). "While the initiating cells in recurrent tumors were mainly related to the cell cycle such as MKI67, CKS2, ANLN, CDC20, CDCA8, CENPF, inflammatory signals no longer drive anti-tumor immunity." (PMID 41601649, 2026).
tumor (continued). "In this study, we investigated the differences in gene expression between normal tissues and tumor tissues, as well as TACE response and non-response groups, and intersected them with MRGs, successfully identifying four key genes (CDC20, LPCAT1, PON1, and SPP1)." (PMID 40404896, 2025). "Regardless of the classification standards (TNM staging/Histology Grade/Vascular invasion) used for analysis, all results revealed that CCNB1, CDC20, and CENPF were already significantly upregulated in the early stages of HCC tumor tissues (T1/G1/Stage I/no vascular invasion)." (PMID 34660300, 2021).
infection (9 papers, 2010 to 2025). The state of being infected such as from the introduction of a foreign agent such as serum, vaccine, antigenic substance or organism. "Infection with Ad-CDC20 increased the CDC20 expression level as compared with that in the control group." (PMID 40045239, 2025). "Numerous CDC genes are differentially expressed in the lung tissue of mice recovering from an acute PVM infection, including Cdc20, Cdc20b, Cdca3, Cdca4, and Cdca7." (PMID 34959580, 2021). "We observed that Cdc20 expression is reduced in SPRY4-IT1-transfected cells after Cdc20 shRNA infection." (PMID 29489909, 2018). "CDC20 expression in mouse hearts was indeed significantly increased following AAV9-CDC20 infection." (PMID 40045239, 2025). "In human IAPA and CAPA patients, genes MAP1LC3B and SQSTM1, related to LAP were decreased, while CDC20, the gene encoding for the CDC20 protein which is involved in LC3 degradation, was upregulated in the superinfection group comparing to viral single infection." (PMID 36377895, 2022). "In subjects with a severe infection, CDC20 is unusually upregulated whilst no activation is seen in hCDH1." (PMID 21408152, 2011).
adenocarcinoma (4 papers, 2012 to 2024). A common cancer characterized by the presence of malignant glandular cells. "The present results also exhibit that among the amplified genes, the following eight genes involved in the cell cycle were found to be amplified in more than 5% of HGSO adenocarcinoma patients: ATAD2, ASF1B, CCNE1, CDC20, CDCA8, RECQL4, RNASEH2A, and SMC4." (PMID 39199556, 2024). "Among them, the mRNA expression of 5 genes, namely, BIRC5, MCM4, CDC20, KIAA0101, and TRIP13, were significantly upregulated among TN adenocarcinomas (all P < 0.05)." (PMID 31093306, 2019). "Results of immunohistochemistry suggest that CDC20 can be a negative marker in prognosis of patients with resected NSCLC, especially adenocarcinoma." (PMID 27610375, 2016).
blood cancer (1 paper, 2022). "In the last years, CDC20 has also attracted more interest in the blood cancer field, being overexpressed and showing an association with prognosis both in myeloid and lymphoid malignancies." (PMID 35490245, 2022).
hematological malignancies (1 paper, 2022). "Despite the low frequency of genetic alterations, CDC20 overexpression and functional deregulation are common events in hematological malignancies, as discussed in the following section." (PMID 35490245, 2022). "In line with evidence from solid cancer, CDC20 overexpression also plays a critical oncogenic role in hematological malignancies." (PMID 35490245, 2022). "The evidence and hypothesis presented in this review provide the input for further biological and chemical studies aiming to dissect novel potential CDC20 roles and targeting strategies in hematological malignancies." (PMID 35490245, 2022).
kidney disease (1 paper, 2025). "To validate the potential genes is functionally in kidney disease, we choose whole genes (CDC16, CDC20, CDC27, MAD2L1, ANAPC1, ANAPC7, BUB1B) from first highest score subnetwork obtained from Cytoscape MCODE plugin from upregulated genes PPI as hub genes." (PMID 40034749, 2025).
CDC20 also shares sentences with these, for which no sentence is quoted: cholangiocarcinoma (5 papers); thyroid cancer (3); brain cancer (2); breast ductal carcinoma (2); ductal adenocarcinoma (2); esophageal cancer (2); lymph node metastasis (2); metastatic prostate carcinoma (2); myocarditis (2); psoriasis (2); acute myeloid leukemia (1); adult T-cell leukemia (1); allergic asthma (1); benign breast tumors (1); brain glioma (1); Burkitt lymphoma (1); chromosomal disorder (1); Chronic Lymphocytic Leukemia (1); chronic obstructive airway disease (1); ductal carcinoma in situ (1); embryonic carcinoma (1); Failure to thrive (1); Fanconi anemia (1); gastrointestinal tumor (1); head and neck tumors (1); hypertrophy (1); idiopathic pulmonary fibrosis (1); immune system diseases (1); intraductal cribriform breast adenocarcinoma (1); invasive breast carcinoma (1).
A further 26 diseases each share a sentence with CDC20 in 1 paper.